CD40 (CD40 molecule)
Diseases named in the same sentence as CD40 in open-access papers (continued):
Sharing a sentence is not in itself a finding about the gene and the disease.
infection (continued). "We choose to follow HLA-DR and CD40 as these markers are well known to be up-regulated when pDCs mature and CD40 expression is increased on pDCs in SIV/HIV pathogenic infection." (PMID 24991927, 2014). "By using previously collected lung and kidney tissue samples from HeV-infected bats, we examined the expression of TRAIL and CD40 mRNA in the context of an in vivo infection." (PMID 25398248, 2014). "As a consequence, these cells were also impaired in their antigenic maturation compared to those from wildtype mice after infection with live L. monocytogenes (lower CD40 expression on CD11c+ cells)." (PMID 24728387, 2014). "To explore potential differential effects of the different PA strains on DC activation, we stained DCs for the activation markers CD86 and CD40 following infection with the different PA strains." (PMID 24587305, 2014). "After infection, CD1c+ DCs expressed HLA-DR, CD40, and CD83 (top) and produced IL-6, TNF-α, and IL-1β but not IL-23, TGF-β, or IL-12p70 (F and data not shown)." (PMID 25071784, 2014). "Similar to our earlier results, treatment of VSV-ova infected mice with 100 μg of agonistic anti-CD40 mAb (FGK4.5) one day after infection resulted in a substantially larger memory CD8+ T cell population." (PMID 25166494, 2014). "Expression levels of CD86, CD80 and CD40 on mDCs were comparable between C3−/− and WT mice during the course of infection." (PMID 23326231, 2013). "A recent study showed, albeit for BCG, that MHC-II, CD80, CD86, and CD40 are down-tuned during chronic phase of infection." (PMID 22719245, 2012). "Infection also induced the expression of co-stimulatory molecules such CD40, CD83, CD86, adhesion molecules (CD38, Itga5, and ICAM1), and tissue invasion molecules such as MMP12 and MMP14." (PMID 22928052, 2012). "Subsequent LVS infection, Acai PS enhanced surface expression of CD11b, CD40, CD80, CD86, TLR2, and MHC class II in a dose-dependent fashion, while TLR4 expression was downregulated in both mock- and LVS- infected macrophages." (PMID 22438809, 2012). "We demonstrated expression of PSMA upon infection of DCs using a CD40-targeted Ad5-huPSMA vector, while using an untargeted vector resulted in undetectable PSMA expression." (PMID 23056548, 2012). "T. annulata- transformed cells were shown to express high levels of CD40 and CD80 and were susceptible to infection with BHV-1, vaccinia and canarypox viruses." (PMID 22182243, 2011). "Swingler and colleagues describe that HIV-1 Nef intersects CD40 signalling in monocytes/macrophages thereby promoting the recruitment and infection of resting T cells." (PMID 21886773, 2011). "CD40−/− died during the chronic phase of infection between weeks 4 to 6 while B6 mice survived at least 11 weeks (p<0.001)." (PMID 21217818, 2010). "Nonetheless, stimulation with infection induced MPs promoted significant up-regulation of CD40 expression and production of TNF by macrophages." (PMID 20126448, 2010). "Despite this, the LPS-induced MPs failed to induce macrophage activation whereas PbA-infection induced MPs induced up-regulation of CD40 expression and production of TNF." (PMID 20126448, 2010). "Our results showed that the expression level of CD40 from GFP positive cells (infected cells) increased from 6 hrs post-infection and continued to increase up to 7 days, and are maximally expressed in transformed EBV positive LCLs." (PMID 19784370, 2009). "In support of this, AM were only transiently and slightly activated, as measured by CD86 and CD40 expression, after infection with MA15." (PMID 19851468, 2009). "The surface expression levels of CD40 on lung macrophages and cDCs collected from adult and aged mice was similar prior to infection (Day 0)." (PMID 19922665, 2009). "To further validate the use of c-Rel-siRNA in primary cells, we stimulated primary B cells with anti-CD40 to trigger cell proliferation 24 hours prior to infection with either the control or c-Rel siRNA expressing retrovirus." (PMID 19347041, 2009).
infection (continued). "Although there is substantial expansion of DC numbers during infection, the CD86hi-CD8αint-CD11b− subset is markedly diminished, and expression levels of CD40, CD86 and CD103 are reduced." (PMID 19766674, 2009). "T lymphocytes produce TNFα after infection with influenza virus, and B lymphocytes produce TNFα after stimulation of the B cell antigen receptor and CD40." (PMID 19002259, 2008). "At 0, 12 and 18 h following infection, cells were harvested and stained with mAbs specific for CD40, CD86, CD80, and MHC class II I-Ad." (PMID 18412969, 2008). "DCs isolated from spleens of mice 4 days after infection showed a moderately activated phenotype, as demonstrated by increased expression of CD40 and CD80, confirming previous reports." (PMID 16611373, 2006). "DCs isolated from infected animals 12 and 20 days after infection, however, showed a reduced level of activation, with lower levels of CD40, CD80, CD86 and MHC class II molecules on their surface compared with DCs from uninfected animals." (PMID 16611373, 2006). "Moreover, genes involved in antigen presentation (e.g., Fcgr1, Tap1, and Cd40) gradually increased over the course of infection in WT microglia, whereas in Mavs−/− microglia they remained unchanged." (PMID 39425188, 2024). "A similar result was shown in the infection of BMDC with L. infantum, where the inhibition of PI3K/Akt by wortmannin before BMDC infection caused a slight increase in the transcription of costimulatory molecules CD40 and CD86." (PMID 38787051, 2024). "Relative to WT control mice, CD40−/− mice challenged intranasally with influenza A virus (IAV) (PR8) exhibited elevated viral lung titers as early as 3 days following infection and decreased lung function as measured by whole-body plethysmography, as well as increased mortality." (PMID 37376652, 2023). "While both strains of mice had elevated PenH scores and decreased minute volume as PR8 infection progressed, the effects were significantly more pronounced and occurred earlier in the CD40−/− mice, indicative of decreased lung function within three days of infection." (PMID 37376652, 2023). "Interestingly, CD40L blockade in WT, but not uMT animals, enhanced control of splenic Brucella burdens four weeks post infection, indicating the deleterious effect of CD40:CD40L interactions is B cell dependent." (PMID 37721965, 2023). "Consequently, the infection induced apoptosis in cholangiocytes via the CD40 molecule (CD40), caspase recruitment domain family member 8 (CARD8), and serine/threonine kinase 4 (STK4)." (PMID 37958904, 2023). "The results of bone marrow and peritoneal cell transfers in our rVSV-EBOV GP model provide evidence that hematopoietic cells, and specifically pMφs, are a key CD154-responsive population in the context of peritoneal infection, with pMφs being responsible for CD40 signaling early in infection." (PMID 37376652, 2023). "However, infection of BMDCs with LDPm led to a gradual decrease in LPS-stimulated CD40, CD80, and CD86 expression, with peak inhibition observed at 24 h postinfection." (PMID 35924848, 2022). "Moreover, it was observed that the expression of IL-12, IL-6, TNF-α, HLA-DR, and CD40 by monocytes-derived DCs was drastically reduced after infection." (PMID 35720410, 2022). "The CD40 dyad was first identified for its role in B-cell activation for antibody production and proliferation of inflammatory cells such as macrophages and lymphocytes in response to infection." (PMID 35456932, 2022). "In response to infection, both CD40 and CD40L are presented on the surface of B and T-cells respectively, which, upon ligation, activates B-cells for antibody isotype switching and upregulates the production of pro-inflammatory cytokines in attempt to neutralize the pathogen." (PMID 35456932, 2022). "This SARS-CoV-2 induced upregulation of CD40 was more pronounced upon infection of M2 macrophages." (PMID 34122407, 2021).
infection (continued). "Interestingly, exosomes secreted by microglia during TMEV infection had increased levels of co-stimulatory molecules, CD80, CD86, CD40, on the surface compared to exosomes secreted by microglia during mock infection." (PMID 34485270, 2021). "To summarize, the abnormal expression of CXCL10, ICAM1, CD40, IRF7, and B2M may be the main cause of tracheal dysfunction after infection with coronavirus." (PMID 34504502, 2021). "However, it has been shown that cross-linking the BCR of infected cells along with CD40 stimulation induces viral reactivation, so it is possible that infection of virus specific germinal center B cells would result in cell death due to lytic replication." (PMID 32353066, 2020). "Further, to verify whether LD inhibits CD40 expression induced by other DC maturation stimuli, we analyzed the effect of LD infection on tumor necrosis factor alpha (TNFα)-stimulated CD40 expression." (PMID 33370418, 2020). "In line with the increased CD40 gene expression following P. falciparum infection, we observed increased CD40 cell surface expression on all three monocyte subsets, with expression also remaining significantly elevated 45 days after infection." (PMID 32566226, 2020). "Since malignant plasma cells express similar molecules as professional antigen-presenting cells, we hypothesized that infection with CD40L expressing LOAd viruses could further alter the phenotype of MM cells as seen by others with CD40 stimulating therapy." (PMID 32355275, 2020). "Burn injuries are highly susceptible to infection and in a human ex vivo burn model, thermal injury induced LC and DC emigration from the skin, with upregulation of MHC II and costimulatory molecules such as CD80, CD86 and CD40." (PMID 30696002, 2019). "Together, these data indicate that 3AKO and in particular 3CKO infection might benefit from CD40 stimulation for persistence." (PMID 29709016, 2018). "Expression of an array of cytokines (CSF3 [G-CSF], IFNγ, IL-1β, IL-6, IL-22, IL-17A, and IL-10), chemokines (CCL20, CXCL2 and CXCL9) and receptors (CD40) known to be involved in the regulation of S. pneumoniae inflammatory response was measured at 0, 6, 24, and 48 h post-infection." (PMID 30333823, 2018). "However, we observed an increased expression of IL-17A and CD40 in lung homogenates of WT in comparison with Ghrh−/− mice 48 h post-infection." (PMID 30333823, 2018). "Our studies on understanding the role of CD40 costimulation in Th17 responses significantly extend our understanding of the CD40-CD40L pathway during infection, as previous investigations studying this pathway in TB as well as in other infections have focused on Th1 responses." (PMID 28767735, 2017). "Similarly, ΔN146 infection resulted in significant increase in the number of CD40-positive and CD86-positive CD11c+ DCs compared to the mock group." (PMID 28150813, 2017). "CD40 has previously been implicated in generating Th1 responses during Mtb infection, but its role in the polarization of the Th17 subset during infection is not defined." (PMID 28767735, 2017). "CD40 has been shown to promote Th1 responses by synergizing with TLR signaling to induce high levels of IL-12 production from antigen presenting cells in several infections." (PMID 28767735, 2017). "These are values in the ranges reported for L. major that in experiments with an MOI of 10 diminished the cholesterol content in macrophages derived from BALB/c mice by about one‐third 72 hr after infection and this correlated with altered CD40 signalosome composition and function." (PMID 28349644, 2017). "MHC class II, CD86 and CD40 expression on splenic pDCs remained unchanged during S. mansoni infection, indicating that the liver is a major site of pDC activation in this infection model." (PMID 26657145, 2016).
infection (continued). "sCD40L is produced mainly by platelets upon activation, therefore, our data indicates a role for CD40-40L interaction in dengue infection which may lead to activation of platelets at early stages of infection." (PMID 26982706, 2016). "In this regard, we should emphasize that the CD40/STING/IFN-I protective mechanism we observed in this N67/C57BL/6 mouse model may only apply to infections with parasite strains that can simulate strong IFN-I responses." (PMID 27716849, 2016). "The mechanisms of CD40-mediated protection are likely different among the models of various disease severities because dramatically different host responses were observed in infections with different parasite strains." (PMID 27716849, 2016). "Furthermore, a greater percentage of conventional and interstitial dendritic cells from Nox1*/Y draining lymph nodes expressed the co-stimulatory ligand CD40 within 6 days post-infection." (PMID 26910342, 2016). "There was, however, a significant increase of CD40 expression on plasmacytoid DCs in spleens of mice treated with ATc, a surprising finding given that this subset of DCs is not known to present parasite antigens to T cells during a blood-stage infection." (PMID 26886275, 2016). "Another important molecule in host immune response to infections is CD40 (or TNF receptor superfamily member 5, TNFRSF5) that is a receptor expressed on the surfaces of many cell types, including B-cells, monocytes, dendritic cells, endothelial cells, and epithelial cells." (PMID 27716849, 2016). "Protein bands could be detected from 12–48 h using antibodies against DDK-tag fused to CD40 and against N’- or C’-termini of CD40 (a small band could be seen 12 h post infection using anti-C-terminus and anti DDK tag)." (PMID 27716849, 2016). "However, by 15dpi EBVΔE3C and EBVΔ621–675 recombinants showed levels approximately 50% of CD19+CD40+ cells when compared with EBV GFPΔE3C and EBNA3CΔ621–675 infection which were significantly reduced for CD40 activation." (PMID 26336822, 2015). "Interestingly, deletion of the Nm23-H1 binding site within EBNA3C had a dramatic effect on its ability to activate CD40 on infected B-cells early during infection." (PMID 26336822, 2015). "Therefore Nm23-H1 binding plays a major role in EBV-mediated CD40 activation of B cells-during early infection." (PMID 26336822, 2015). "By generating mice deficient in both MyD88 and CD40, we set out to elucidate whether synergy between MyD88 and CD40 influences the anti-bacterial immune response during infection with a live pathogen." (PMID 26441965, 2015). "After infection, they upregulated HLA-DR and CD40, which are required for CD4+ T cell priming." (PMID 25071784, 2014). "Agonistic CD40 stimulation during CD8+ T cell priming in response to VSV infection enabled the resultant memory CD8+ T cell population to provide strong protective immunity against secondary infection." (PMID 25166494, 2014). "To determine whether TRAIL and CD40 mRNA is induced during HeV infection in vivo, we utilized previously collected tissue samples from an experimental infection of the Australian black flying fox." (PMID 25398248, 2014). "Importantly, treatment of VSV infected mice with 100 μg of agonistic anti-CD40 mAb (FGK4.5) one day after infection resulted in a nearly three-fold larger memory CD8+ T cell population." (PMID 25166494, 2014). "Furthermore, CD11c+F4/80− cells had the highest percentage of MHC II+ CD40+ cells after infection (about 23%), whereas about 12% of CD11c+F4/80+ cells expressed both molecules." (PMID 23390557, 2013). "Third, we use retroviral shRNA infection to perturb the amount of CD40 on the surface of a human B lymphocyte cell line (BL2) and observe a direct correlation between amount of CD40 protein and phosphorylation of RelA (p65), a subunit of the NF-κB transcription factor." (PMID 23696745, 2013).
infection (continued). "However, if anti-CD40 treatment was combined with a LCMV8.7 infection P14.IFNARKO T cells initially expanded but then dramatically crashed." (PMID 22815848, 2012). "In the current study, microarray analysis showed that CD40 was upregulated at all time points post-infection, while CD40 signalling was the 7th highest ranking canonical pathways identified 2 hpi, supporting an important role for this macrophage receptor during M. avium subsp." (PMID 22455317, 2012). "Interestingly, CD40−/− mice infected with E. multilocularis produce specific IgM, IgG2b and IgG3 antibodies after 2 months of infection." (PMID 21912714, 2011). "Cell surface CD40 on lung macrophages was significantly up-regulated within 2-3 days post-infection in adult mice, but did not increase on the same cells from aged mice until day 5 post-infection." (PMID 19922665, 2009). "In the case of CD40, a downshift in expression was detectable on CD8αlo and CD8αhi populations, which in combination with their higher frequency following infection and their lower consitutive levels of CD40, reduces the overall intensity of this marker within the MLN DC population." (PMID 19766674, 2009). "Interestingly, even though all cell lines were sensitive for LOAd infection, the CD40 positive cell lines, T24 and PEA2, had significantly reduced viability after infection with TMZ‐CD40L‐expressing LOAd viruses, as compared to after infection with LOAd(−), that lacks transgenes." (PMID 38494863, 2024). "Similarly, infection of DCs with a low pathogenic tick-borne flavivirus (Langat virus, LGTV) was reported to inhibit DC activation through defective IL-12 production and weak up-regulation of CD40, CD86, and MHC class II surface expression." (PMID 37707204, 2023). "Interestingly, determination of the level of expression of macrophage antigen presentation/processing and activation markers (MHCII, CD80, CD86 and CD40) by flow cytometry after 48 h of infection revealed that all markers were significantly increased in cells infected with the sucT mutant." (PMID 37669276, 2023). "Therefore, we can infer that the upregulation of CD40 means that such a mechanism may also exist in Ct infection." (PMID 33875006, 2021). "In addition, microglia related genes, and genes associated with microglial cell activation (Mki67, Cd40, Tmem119 and Cx3cr1) were significantly induced 4 days following VACV-Wyeth infection indicating the possible role of these cells in the induction of immune response in the brain." (PMID 30759813, 2019). "In order to verify whether these proteins are involved in cAMP-mediated DC inhibition, cells were infected by L. amazonensis in the presence of KT5720 or LY294002, known inhibitors of PKA and PI3K, respectively, and after 20 h of infection, CD40 expression and cytokine production were evaluated." (PMID 28791011, 2017). "However, when we supplemented a strong CD40 stimulus for the first days after infection, ΔLMP2A LCLs and WT LCLs could be generated with similar yield, and ΔLMP2A LCLs could then be maintained autonomously." (PMID 26067064, 2015). "However, when anti-CD40 treatment was combined with a LCMV8.7 infection, P14.IFNARKO T cells initially expanded until day 5 and crashed dramatically thereafter, indicating that a direct type I IFN signal is a crucial survival factor for the already expanded T cells in this situation." (PMID 22815848, 2012). "Therefore, it is intriguing to speculate that in the chronic phase of infection, mycobacteria may hamper CD40 expression or manipulate CD40L signaling through binding with HSP70 instead of CD40L in order to evade host defense mechanisms." (PMID 22719245, 2012). "As these mice lack transgene-driven pancreatic expression of TGF-β, this model allow us to directly test the hypothesis that the reduction of CD40 on the surface of CD11b+CD11c− APCs following infection in the context of TGF-β is part of the mechanism that favors Treg increases." (PMID 22355341, 2012).